SLFN12 (schlafen family member 12)
Diseases named in the same sentence as SLFN12 in open-access papers (continued):
Sharing a sentence is not in itself a finding about the gene and the disease.
tumor (21 papers, 2017 to 2025). "The lower overall survival seen in this patient subgroup may be related to the decreased susceptibility to temozolomide in high SLFN12‐expressing tumours." (PMID 39740094, 2024). "The survival curves suggest that a low SLFN12 expression in the tumor is associated with a poor prognosis for SLFN12 alone as well as for all of the gene signatures identified, with better survival prediction capabilities for the SLFN12 gene signature than for SLFN12 alone." (PMID 36672349, 2023). "Vlnplot shows the SLFN12 expression in the microenvironment cells in the GBM scRNA‐seq dataset, in which SLFN12 was highly expressed in tumour cells." (PMID 39740094, 2024). "When coupled with phosphodiesterase 3A (PDE3A), SLFN12 can increase tumor sensitivity to 6-(4-(diethylamino)-3-nitrophenyl)-5-methyl-4,5-dihydropyridazin-3(2H)-one (DNMDP) in lung adenocarcinoma cell lines." (PMID 38832156, 2024). "Functional studies revealed that SLFN12 is involved in key immune‐related pathways, shedding light on its potential role in altering the tumour microenvironment and impacting immunotherapy outcomes." (PMID 39740094, 2024). "Stable SLFN12 overexpression reduced tumorigenesis, increased tumor latency, and reduced tumor volume." (PMID 36672349, 2023). "At the end of the study, mammary xenograft tumors of LV-SLFN12 demonstrated a higher SLFN12 expression (53.32 ± 7.92-fold versus 1.01 ± 0.07-fold in empty vector tumor, n = 3, p < 0.01)." (PMID 36672349, 2023). "We sought to explore SLFN12 overexpression effects on in vivo human TNBC tumor xenograft growth and performed RNA-seq on xenografts to investigate related SLFN12 pathways." (PMID 36672349, 2023). "Our present results now demonstrate that SLFN12 expression in vivo reduces tumorigenesis, increases tumor latency, and leads to a significantly smaller tumor volume." (PMID 36672349, 2023). "Many studies have found that SLFN12 played a key role in generating anti-tumor effects triggered by certain drugs or interventions." (PMID 34040636, 2021). "Our knowledge of the physiological functions of the PDE3A and SLFN12 pathway has just begun to emerge: from tumor suppressor to placental implant." (PMID 34707099, 2021). "Four gene modules appeared differentially correlated with SLFN12 depending upon the histological subtype of the tumor." (PMID 32987632, 2020). "SLFN12 was faintly detected with immunohistochemistry (IHC) in the tumor tissue." (PMID 39930717, 2025). "Therefore, mRNA in situ hybridization has been proposed as a potentially more reliable method for estimating SLFN12 expression in tumor tissue." (PMID 40527986, 2025). "Furthermore, SLFN12 levels have been shown to not only affect intrinsic TNBC tumor biology but also the response to treatment by sensitizing TNBC to radiation and cytotoxic drugs." (PMID 39594803, 2024). "One possibility is that SLFN12 may play a role in modulating the immune infiltration or functional status of the tumour microenvironment, thereby influencing the efficacy of immune checkpoint blockade." (PMID 39740094, 2024). "How PDE3A recruitment of SLFN12 results in tumor cell death is still to be determined." (PMID 28421158, 2017). "The neoepitopes ISSKFKSKR (DDX47) and IEIEDTFETLW (TGFBI) corresponded to category V, and HSTLQKSLW (LRR1) together with KLRKKQNER (SLFN12) neoepitopes corresponded to category TV, being expressed both in VACCIMEL and patient #032’s tumor." (PMID 39840067, 2024). "In vitro, SLFN12 overexpression reduces TNBC cell viability, promotes tumor cell differentiation, and reduces tumor proliferation, perhaps leading to more favorable tumor biology." (PMID 38067362, 2023). "The results showed that the high SLFN5, SLFN11, SLFN12, SLFN12L, and SLFN13 expression in GC was positively correlated with lymph node metastasis, tumor stage, and tumor grade." (PMID 36090985, 2022).
tumor (continued). "Extending these molecular insights, we show in vivo that nauclefine inhibits tumor xenograft growth, doing so in a PDE3A- and SLFN12-dependent manner." (PMID 32591543, 2020). "Among these 20 common genes, the expression levels of CDK20, AKAP7, AZIN2, LIX1L, OSCP1, and SLFN12 were upregulated, while HLF was downregulated in TC-PD-L1+ tumours (Pattern 3 and Pattern 4)." (PMID 29921949, 2018). "However, the potential of these metabolites to act as molecular glues between PDE3A and SLFN12 remains unexplored, despite the fact that ANA drug sensitivity in tumor cells is thought to mostly correlate with these protein expression levels." (PMID 39930717, 2025). "Nevertheless, our tumor growth and survival data indicated that such increases did not abolish the effect of SLFN12." (PMID 36672349, 2023). "Moreover, the inhibition of tumor growth by nauclefine was dependent on the expression of both PDE3A and SLFN12." (PMID 32591543, 2020). "Furthermore, SLFN12 has been reported to sensitize TNBC to chemotherapy and radiation, indicating that SLFN12 levels may affect both the intrinsic tumor biology and the tumor’s response to treatment." (PMID 38067362, 2023). "The results demonstrated that SLFN5, SLFN11, SLFN12, SLFN12L, and SLFN13 expression in tumor tissues was significantly higher than that in normal tissues in paired, and unpaired tests, implying that they may play a role in promoting tumor progression in GC." (PMID 36090985, 2022). "SLFN12 and PDE3A are not known to play a role in oncogenesis or to be required for tumor maintenance, and they are not known to be essential genes for cell survival." (PMID 39166256, 2024).
infection (5 papers, 2013 to 2024). The state of being infected such as from the introduction of a foreign agent such as serum, vaccine, antigenic substance or organism. "The primary RNA-seq data showed that P25.M upregulated the SLFN12 and ZFN transcripts at an earlier infection stage than P25.5." (PMID 39456264, 2024). "In addition, six genes (SLFN12, MX2, TRIM30A, GBP1, GBP6, and IFIH1) were common to 15 dpi and the early infection period." (PMID 29147886, 2018).
adenocarcinoma (1 paper, 2020). A common cancer characterized by the presence of malignant glandular cells. "Overexpression of SLFN12 significantly reduced mRNA levels of the adenocarcinoma differentiation marker SCGB1A1 in all of the LUAD cells studied (HCC827, H23, and H1075) and in one LUSC cell line (H2170 cells) compared with treatment with AdCMV as a control." (PMID 32987632, 2020). "The median survival for patients with adenocarcinoma who expressed high levels of SLFN12 was 117.3 months versus 73.3 months in patients with low SLFN12 expression." (PMID 32987632, 2020). "Our results raise the possibility that SLFN12 may act in adenocarcinoma at least in part by its effects on c-myc and its downstream signals, but SLFN12 may affect a variety of transcription factors and the interplay between them and their downstream effects is likely to be complex." (PMID 32987632, 2020).
SLFN12 also shares sentences with these, for which no sentence is quoted: viral infection (2 papers); Allergy (1); asthma (1); experimental autoimmune encephalomyelitis (1); Hashimoto thyroiditis (1); measles (1); non-small cell lung carcinoma (1); pneumonia (1); renal cell carcinoma (1); rheumatoid arthritis (1); Sepsis (1); short gut syndrome (1); small cell lung carcinoma (1); systemic lupus erythematosus (1); Thrombocytosis (1).